CD14 (CD14 molecule)
Diseases named in the same sentence as CD14 in open-access papers (continued):
Sharing a sentence is not in itself a finding about the gene and the disease.
tumor (continued). "Our finding that simultaneous inhibition of IL-6R and CSF1R drastically reduces tumor-induced cDC2 to CD14+ DC conversion creates several therapeutic possibilities." (PMID 38242119, 2024). "We detected IL-6 and M-CSF, present in tumor-CM and patient serum, as inducers of CD14+ cDC2s from cDC2s." (PMID 38242119, 2024). "The readout included human CD14 (myeloid cells), EGFRvIII (antigen-positive tumor cells), and NESTIN (pan-GBM cell marker) IF stainings." (PMID 39521782, 2024). "LUAD tumor cells have been shown to recruit CD14+ monocytes, and patients expressing high levels of CD14+ cells in their tumors were found to have worse prognosis when compared with their CD14mid and CD14lo counterparts." (PMID 38716730, 2024). "Both CD14+APOE+ cells and MMP7+ tumour cells were associated with poorer survival outcomes and unfavourable immunotherapy response, underscoring their potential as biomarkers in NSCLC." (PMID 39187937, 2024). "We then identified cells exhibiting positive staining for specific markers, including PanCK (tumour marker), CD14 and APOE." (PMID 39187937, 2024). "The tumour promoting roles of IL-10+ MDSCs are not limited to solid tumours, as IL-10-producing CD14+HLA-DR– MDSCs have also been observed in patients with non-Hodgkin’s lymphoma and negatively correlated with anti-tumoural NK cell abundance." (PMID 38464388, 2024). "In contrast, none of the BLM-CM-induced CD14+ cDC2s lost CD14 expression, suggesting that contact with tumor-secreted factors alters the plasticity, thereby prohibiting the reversion of CD14+ DC2s to CD14− cDC2s." (PMID 38242119, 2024). "CD14 + CTLA-4+ tolerogenic DCs are a regulatory DC subtype that can suppress the anti-tumor immune response of CTLs via IL-10 and indoleamine-2,3-dioxygenas." (PMID 38791916, 2024). "The increased frequencies and low immunostimulatory capacity of CD1c+CD14+ cells urged us to study their development in tumor context." (PMID 38242119, 2024). "EPCAM and KRT8 were abundantly expressed in tumor epithelial tissue with scattered expression of CD14 and CD163 in monocytes/macrophages." (PMID 38611120, 2024). "In a tumor context, another layer of complexity is added to the origin and development of CD1c+CD14+ DCs." (PMID 38242119, 2024). "Together, this indicates cDC2s as direct pre-cursors of DC3-like CD1c+CD14+ DCs and provides insights into the importance and modulation of CD14+ DC3s in anti-tumor immune responses." (PMID 38242119, 2024). "The combination of CD84 and JAML cell surface receptors on MDSCs with CD11b/Gr1 staining detects the presence of MDSCs in mouse tumor tissues or in humans with CD11b/CD14 or CD15." (PMID 38609997, 2024). "In regard to OS, patients with higher percentages of PD-L1+ CD14+ cells and high tumor PD-L1 expression exhibited longer OS." (PMID 38790920, 2024). "Both CD14+APOE+ cells and MMP7+ tumour cells were associated with poorer survival outcomes and immunotherapy therapy response, underscoring their potential as therapeutic targets." (PMID 39187937, 2024). "Nevertheless, studies in human MDSCs found that both CD11b+CD15+HLA-DRlow/– G-MDSCs and CD11b+CD14+HLA-DRlow/– M-MDSCs can upregulate ROS production in response to tumour-conditioned-supernatant and suppressed T cell proliferation in vitro." (PMID 38464388, 2024). "Macrophages play roles in PDAC development; CD14 signaling induced by lipopolysaccharide was reported to “retune” immunosuppressive M2 macrophages, converting them to a tumor-suppressive phenotype." (PMID 38672675, 2024). "Our in vitro experiments furthermore showed that anti-IL-6R and CSF1Ri effectively prevent the development of tumor-induced CD14+ cDC2s." (PMID 38242119, 2024). "In summary, prevention of tumor-induced CD14+ cDC2s can be achieved with tocilizumab and sunitinib leading to an improved immunostimulatory capacity of cDC2s." (PMID 38242119, 2024).
tumor (continued). "After having observed the influence of the tumor on CD1c+CD14+ cell frequencies, we continued with investigating potential precursors of tumor-induced CD1c+CD14+ cells." (PMID 38242119, 2024). "Our findings align with the transcriptomics study, as we detected the presence of MMP7+ tumour cells and CD14+APOE+ cells in the NSCLC tumour region." (PMID 39187937, 2024). "The cell‒cell communication between MMP7+ tumour cells and CD14+APOE+ cells was consistent with the results based on the ST data." (PMID 39187937, 2024). "CD14 has been shown to be related to tumour relapse, proliferation, metastasis and chemoresistance, all of which are features of cancer stem cells." (PMID 39816386, 2024). "The expression of specific markers CD3+ for T lymphocytes, CD19+ for B lymphocytes, CD56+ for NK cells, and CD14+ for monocytes/macrophages was used to assess immune cell infiltration within the tumor." (PMID 39493451, 2024). "Then, primed DCs were added to CD14‐ cells from the corresponding donors to enable the development of tumor‐specific T cells, as detailed in the Methods section." (PMID 38818122, 2024). "Following recruitment, Notch-activated macrophages suppress the proliferation of tumor-infiltrating T cells and their tumor-killing activity by enhancing CD14 and CD93 secretion." (PMID 39766289, 2024). "Conversely, macrophages, derived from CD14+ cells (monocytes), comprise a substantial portion of the tumor microenvironment and wield significant influence over tumor progression." (PMID 39000195, 2024). "Our work highlights the plasticity of DCs, provides insights in the development of DC3-like CD1c+CD14+ DCs with cDC2s as pre-cursor, and possibilities to modulate DCs for enhanced anti-tumor responses to improve cancer therapies outcomes." (PMID 38242119, 2024). "Analysis of complex myeloid phenotypes showed CD14+/pSTAT3+ myeloid cells with inflammatory signaling, and CD14+/HLA-DR+ antigen-expressing myeloid cells were found both in the tumor and stroma tissue segments of bone metastases." (PMID 38193534, 2024). "Focusing on preventing tumor-induced CD14+ cDC2s, we investigated licensed drugs for their ability to impede CD14+ cDC2s." (PMID 38242119, 2024). "In patients with hepatocellular carcinoma, CD14(+)HLA-DR(low/−) MDSCs were markedly upregulated in the peripheral blood or tumor tissue." (PMID 38609997, 2024). "Second, while our spatial analysis revealed the co‐location of CD14+APOE+ cells with MMP7+ tumour cells, the functional implications of this co‐localisation were inferred based on known roles of these cell types and their expression profiles." (PMID 39187937, 2024). "A strong correlation was found between the macrophage/monocyte marker CD14 (ρ 0.71, p = 0.027) and tumour volume." (PMID 38480935, 2024). "Increased frequencies of DC3s (CD1c+CD14+) are reported in tumor context but a detailed investigation into their development, characteristics, and plasticity is lacking." (PMID 38242119, 2024). "In order to confirm the presence of CD14+APOE+ cells and MMP7 tumour cells in close proximity, we determined the association between MMP7 and CD14 as well as APOE in a substantial group of NSCLC patients." (PMID 39187937, 2024). "The heterogeneities of myeloid-derived suppressor cells (MDSCs) have been documented, and specific markers such as CD84 and CD14 have been identified within tumor microenvironments." (PMID 38919617, 2024). "CD14+ monocytes are crucial in regulating the tumor's immune response, facilitating tumor proliferation and metastasis." (PMID 38600248, 2024). "The proportional uptake of TDEV by tumour cells and CD14+ cells was 40% and 60%, respectively, indicating that TDEV uptake by myeloid cells still occurs in the presence of tumour cells." (PMID 39763667, 2024). "Targeted proteomics identified IL-6 and M-CSF as dominant drivers, and we show that IL-6R and CSF1R inhibition prevents tumor-induced CD14+ cDC2s." (PMID 38242119, 2024).
tumor (continued). "Altogether, the transdifferentiation from cDC2s to CD14+ cDC2s is dominantly driven by M-CSF and IL-6, secreted by tumor cells and present in serum from cancer patients." (PMID 38242119, 2024). "In conclusion, we revealed that SPP1+ macrophages and CD14+ monocytes were highly associated with immunosuppressive TME and tumor angiogenesis, respectively." (PMID 38600248, 2024). "The ambiguity of these data led us to investigate mifamurtide efficacy on three OS cell lines, characterized by a different degree of malignancy, through in vitro experiments after co-culturing the tumor cells with CD14+ cells (monocytes)." (PMID 37835437, 2023). "CXCL9, CXCL10, and CXCL11 were expressed most prominently by cluster 11, which was annotated as CD14(+) monocytes derived from neoplasms." (PMID 37686653, 2023). "The mechanisms of the disease progression included CCL15-mediated autocrine stimulation of the tumor invasion and recruitment of CCR1+ cells, of which 80% were CD14+ monocytes inducing activity of pro-tumor factors and accelerating metastasis." (PMID 37185750, 2023). "Lewis lung carcinoma (LLC) cell line derived exosomes stimulate MDSC expansion in a mouse tumor model and in CD14+ monocytes in vitro, through a miR-21a-dependent mechanism." (PMID 37915578, 2023). "Tumor-associated macrophages (TAMs) were identified by CD68, CD14, CD163 and HLA-DRA and cancer-associated fibroblasts (CAFs) were characterized by COL1A1, COL3A1, MMP2, and SPARC." (PMID 37007745, 2023). "Here, while they achieved a decrease of CD14+CCR2+ inflammatory monocytes in the peripheral blood samples, only 2 of 21 patients had a decrease CCR2+ tumor associated macrophages." (PMID 37181043, 2023). "The MARCO, CD14, FCGR3A, and CD163 genes, which are unique to tumor-associated macrophages (TAMs), were expressed in cluster two." (PMID 38096229, 2023). "Cancer cells with high CD14 expression show increased amounts of many inflammatory factors, resulting in greater tumor formation than cells with low CD14 expression." (PMID 37071001, 2023). "In the myeloid cell compartment, we found seven clusters, from which clusters 1, 3, and 4 were tumor-associated macrophages (TAM) expressing genes such as HLA-DRB1 and CD14." (PMID 37501683, 2023). "In primary tumors, a high frequency of CD14+ cells and a high level of CCL2 by tumor epithelial cells were associated with early recurrence." (PMID 37208442, 2023). "As a vital target in the TLR signalling pathway, CD14 exerts a dual effect on oncogenesis, which can initiate several tumour-related signalling pathways or alter the immune microenvironment in the tumour." (PMID 36925653, 2023). "When tumor tissues were immunophenotyped, we found that CD11b+/CD14+ macrophages in anti-PSGL-1-treated mice had a 1.8-fold upregulation of MHC-II M1 marker expression." (PMID 37819238, 2023). "Tumor ROIs in BM-LUAD expressed higher expressions of CD14, CD163, GZMA, BCL-6, BAD, BCLXL, 4-1BB, VISTA, and IDO1." (PMID 37061716, 2023). "These included B cells (BC_IGHG1_PRDM1), fibroblasts (FB_CALB2, FB_CFD, FB_COL27A1, FB_COMP, FB_MYH11, FB_RGS5, FB_SERPINE1), myeloid cells (M_CCL18, M_CCR2, M_CD14), and tumour cells (Tum_KRT6A, Tum_TNNT2)." (PMID 37370765, 2023). "We then assessed the impact of FaDu tumor cells on the polarization state of monocytes CD14+ in the coculture spheroid model." (PMID 37628994, 2023). "Multicolor immunofluorescence staining of PDX tumors demonstrated that human immune cells, including CD3+ T cells, CD14+ and HLA-DR+ myeloid cells, penetrated deeply into the tumor and co-localized with tumor cells as well as with other engrafted immune cells." (PMID 37487666, 2023). "In our study, CD14-positive cells in tumor samples were mainly macrophages and bone marrow-derived monocytes found to exhibit tumor-promoting and immunosuppressive effects." (PMID 36969247, 2023).
tumor (continued). "Compared to adjacent normal tissues, tumor tissues exhibited overall increases in DCs, CD14 monocytes, and CD16 monocytes, indicating a redirected immune response." (PMID 38149248, 2023). "Results show that C3AR1 has the strongest correlation with M2 macrophages (CD163, MRC1, CD209), tumor-associated macrophages (CCL2, CD86, CD68) and monocyte immune markers, including (CD14, CD33, ITGAX)." (PMID 37005667, 2023). "It was also shown that the number of monocytes characterized by the CD14+ human leukocyte antigen (HLA)-DRlow immunophenotype was elevated according to the tumor stage and poor survival." (PMID 35359385, 2022). "We went on to confirm the correlation among CA12, HIF1α, and cytokine expression in HCC tumor tissue–purified CD14+ cells." (PMID 35362480, 2022). "It was demonstrated that PFKFB3 is predominantly expressed on CD14+CD68+ monocyte-derived macrophages that massively infiltrate tumor tissue." (PMID 36733385, 2022). "We observed that some patients’ NK cells have performed an astonishingly efficient trogocytosis and capture of antigens from target cells, i.e., CD19 from the tumor B cells of a B-cell lymphoma patient or CD14 from the tumor cells of an AML patient and so on." (PMID 35632444, 2022). "After gating on live CD45+Lineage-MHCII+ cells, we used CD11c and CD14 to identify CD11c+CD14+ tumor-associated macrophages (TAM) comprising CD16+ TAM and CD16- TAM, CD11c+CD14- DC and CD11c-CD14- cells." (PMID 36325333, 2022). "Studies have shown that the CD14 gene is related to macrophage differentiation and regulates immune cell activation and is closely related to tumor cell proliferation and the tumor microenvironment in cancers." (PMID 35774505, 2022). "The roles of lymphoid cells such as CD4+ TILs and CD8+ TILs have been well elucidated in anti-tumor responses, while the complex role of myeloid cells such as CD14+ monocytes and CD15+ granulocytes have been relatively underexplored." (PMID 36203421, 2022). "Meanwhile, GPX8 mRNA expression was significantly correlated with monocyte marker CD14, dendritic-cell marker NRP1, natural killer cell marker B3GAT1, neutrophil marker CCR7, and tumor-associated fibroblast marker FAP." (PMID 36061208, 2022). "Correlation analysis of six prognostic MDGs (ABCG1, KDF1, KITLG, TGFA, HAVCR2, and CD14) and six types of immune infiltrating cells, including tumor purity, B cells, CD8+T cells, CD4+T cells, macrophages, neutrophils, and dendritic cells was performed." (PMID 35774505, 2022). "A relationship between the ercDC from RCC tumor tissue and myeloid cells from chronic inflammatory kidney pathologies was previously suggested based on the triple marker staining of CD14, CD209 and CD163." (PMID 36291154, 2022). "Some signaling molecule triggers such as Biglycan can regulate inflammation through CD14 to influence tumor progression." (PMID 36479102, 2022). "The presence of THCs (CD45+CD14+EpCAM+) was observed in paired tumour, peritumour and metastasis tissue samples from CRC patients." (PMID 35884505, 2022). "Chemotherapy resistance is a major clinical challenge, and we tested if CD14+ cells reduced tumor sensitivity to cisplatin." (PMID 36139660, 2022). "As the dexamethasone-treated cells, every tumor cell line-derived-CM induced the generation of CD14 and DC-SIGN double-positive moDCs." (PMID 36194602, 2022). "For the APC panel, FAUST identified several tumour-enriched phenotypes of CD14+ cells, cDC2s and cDC3s marked by co-expression of CD40 and PD-L1, resembling an activated APC phenotype." (PMID 35545675, 2022). "In addition, the higher expression of fibroblast growth factor 2 (FGF2) and CD14 can be associated to the great ability of WT spheroids to influence the other cellular components of tumor microenvironment, such as fibroblasts and monocytes positively supporting tumor development." (PMID 36230687, 2022).
tumor (continued). "We only retained myeloid cells in clusters 12, 14, and 20 and removed tumor cells in cluster 12 according to examine the expression of CD14 and FCER1G genes." (PMID 35493068, 2022). "Tumor cell-macrophage hybrids express both macrophage (CD14, CD68, CD163, CD204, and CD206) and tumor-specific markers (ALCAM, MLANA, KRT, EpCAM, CXCR4, and CD44)." (PMID 35242760, 2022). "In bladder carcinoma, there are increased numbers of MDSCs with CD14+HLA-DR−/low compared with controls, and the level was related to sex, tumor number, tumor size, pathological grade, and clinical stage." (PMID 40636417, 2022). "The enrichment of CD14+ cDC2 was also observed in other tumor types like metastatic melanoma, leukemia, breast, lung and colorectal cancers." (PMID 36230990, 2022). "Clinically, an increasing burden of peripheral-blood-circulating CD14+HLA-DRlo/neg cells correlates with poor patient outcomes across multiple tumor types, including NSCLC." (PMID 36139660, 2022). "We investigated the impact of tumor cell-derived conditioned media on the differentiation of DCs from CD14+ monocytes, sequentially determining the phenotype, cytokine production, phagocytic, and the T cell polarizing capacity of moDCs." (PMID 36194602, 2022). "The expression levels of CA12 and glucose transporter GLUT1 showed positive correlation in tumor purified CD14+ cells." (PMID 35362480, 2022). "Activated macrophages that circulate in the blood and harbour tumour-derived protein epitopes (possibly also from CTSs or EV’s) can be detected by antibodies (CD14 and CD16) via the non-invasive EDIM technology." (PMID 35864157, 2022). "The detection of Apo10 in CD14+/CD16+ monocytes above a certain threshold indicates phagocytosis of tumor compounds." (PMID 36009359, 2022). "We and others have reported the tumor-driven phenotypic and functional changes in CD14+ cells after coculture." (PMID 36139660, 2022). "Our result suggests that tumor cell lines and dexamethasone alter the epigenetic regulation of the CD14 and DC-SIGN expression in moDCs." (PMID 36194602, 2022). "Western blotting showed that sh‐E2A significantly increased the levels of CD11b and CD14 proteins and inhibited the expression of cyclin D3 and p‐Rb compared with the control tumours." (PMID 35001521, 2022). "Classical CD14+CCR2+ monocytes infiltrate neoplasms and contribute to the majority of myeloid cells within the tumor microenvironment, but they are eventually reprogrammed into pro-tumoral monocyte-derived cells by the cancer niche." (PMID 35493454, 2022). "Among them, Module2 (highly express RNASE1, C1QA, CD163, CD14, C1QC, FCGRT, and MS4A7) and Module10 (highly express APOC1, CTSB, CTSL, and TYROBP) are more likely to display the characteristics of tumor-associated macrophages (TAMs)." (PMID 35990663, 2022). "Our results suggest that tumor cell supernatants and dexamethasone alter the epigenetic regulation of moDCs’ CD14 and DC-SIGN expression differently." (PMID 36194602, 2022). "Among the three groups, the abundance of CD14 cell clusters is the most of all the cell clusters, which indicates a vital role of CD14 in tumor immune response." (PMID 35812372, 2022). "Both tumor and colon had a large proportion of CD14+ MPs within the HLA-DR+ APCs, and CDC2 were proportionally higher than CDC1 in colon." (PMID 34680397, 2021). "Searching for the informative biomarker for the systemic cross-talk between the growing tumor and the innate immune system, we found a high percentage of HLA-DR-positive cells within the CD14+16- subpopulation of monocytes." (PMID 35237501, 2021). "CD14 was among the 28 IRGs, and BC cells with high CD14 expression have been shown to produce tumor-promoting inflammation and promote tumor cell proliferation." (PMID 34266411, 2021). "Lastly, tumor-associated moDC are derived from Ly6C+ (mice) or CD14+ (humans) monocytes and are characterized as CD11c+ MHC-II+ F4/80− CD64+ in mice and CD14+, sometimes CD16+ in humans." (PMID 33859645, 2021).